H19 (H19 imprinted maternally expressed transcript)
Diseases named in the same sentence as H19 in open-access papers (continued):
Sharing a sentence is not in itself a finding about the gene and the disease.
tumor (continued). "The long noncoding RNA, H19, has been shown to be markedly overexpressed in individuals with NEPC, and studies have confirmed that H19 not only triggers differentiation of PCa into NEPC but also bolsters resistance of tumor cells to ADT." (PMID 40303302, 2025). "Upregulated H19 promotes cell proliferation and invasion, while HOTAIR, promotes tumour growth, metastasis and angiogenesis and is associated with poor prognosis in colorectal cancer." (PMID 39912983, 2025). "H19, typically oncogenic in other cancers, serves as a tumor suppressor in metastatic prostate cancer." (PMID 40242248, 2025). "In the context of hepatic cancer, TGF-β promotes tumor development through a newly identified H19 long noncoding RNA signaling axis via SRY (sex determining region Y)-box 2 [SOX2]." (PMID 40260391, 2025). "We found that the expression of 9 DE-ceRNAs were significantly different between tumor tissues and normal tissues, including the upregulated H19, HOTAIR, miR222, miR148a, PCDHGB4, GMNC and HMGA2 and the downregulated LRP2 and MBP in tumors." (PMID 40351420, 2025). "Of note, the reduction in E-cadherin and β4 integrin expression following JQ1 treatment was also observed in vivo in tumor xenograft mice obtained with the subcutaneous injection of H19-silenced PC-3-luc (siH19) and control vector cells in NOD/SCID mice." (PMID 40407591, 2025). "Functionally, H19 presents a dual nature, acting as both an oncogene and a tumor suppressor gene, depending on cancer type and tumor microenvironment." (PMID 40407591, 2025). "Both miR-675 and lncRNA H19 can act as oncogenes or tumor suppressors depending on the specific cancer type 17." (PMID 39744561, 2025). "Our findings showed that the level of H19 in tumor tissues was negatively correlated with hsa-miR-138-5p and hsa-miR-22-3p (r = -0.50, P = 0.03; r = -0.55, P = 0.01), while H19 was positively correlated with BMP2 mRNA expression (r = 0.98, P < 0.001)." (PMID 40297808, 2025). "His expression is downregulated in PitNET and is correlated with tumor progression, suggesting that H19 acts as a tumor suppressor." (PMID 40362297, 2025). "Functional assays demonstrated that H19 silencing in resistant cells attenuated chemoresistance, suppressed proliferation, migration, invasion, and colony formation in vitro, and delayed tumor growth in vivo." (PMID 41194501, 2025). "A statistically significant difference was observed in genotype distribution between tumor subtypes in the case of H19 rs2839698." (PMID 41463069, 2025). "After continuous incubation for 5 weeks, we observed a significant reduction in tumor volume and mass in the sh-H19 group, whereas tumor volume was notably enlarged and mass increased significantly in the pcDNA-BMP2 group." (PMID 40297808, 2025). "For instance, miR-21 promotes tumor invasion and metastasis by targeting tumor suppressor genes, while long ncRNAs like H19 and MALAT1 modulate epithelial–mesenchymal transition and cell motility." (PMID 40918645, 2025). "qRT-PCR analysis revealed that the combination treatment markedly inhibited lncRNA H19 expression within the tumor." (PMID 38794196, 2024). "Another study on BLCA found that knocking down the H19 gene increased the expression of E-cadherin, affecting tumor cell proliferation and epithelial-mesenchymal transition, ultimately leading to the inhibition of BLCA's invasive ability." (PMID 38594513, 2024).
tumor (continued). "Regarding ceRNA networks, CLRN1 antisense RNA 1 (CLRN1-AS1)/miR-217/ Dickkopf-related protein 1 (DKK1) and H19/miR-93a/autophagy related 7 (ATG7) are the identified tumor suppressive ceRNA that suppresses miR-217 and miR-93a, respectively." (PMID 39702128, 2024). "H19 was initially thought to have tumor-suppressive function because of its ability to inhibit tumorigenesis, but recent studies have now shown that H19 possesses both tumor promoter and suppressive functions." (PMID 39659621, 2024). "The biological function of H19 in most cancer types is oncogenic, and therefore, high H19 expression is generally correlated with enhanced tumor growth, cell cycle progression, EMT induction, and elevated metastasis." (PMID 39403602, 2024). "In CRC, the expression of H19 was found to be remarkably increased in recurrent CRC patient tumor samples." (PMID 39403602, 2024). "Spearman correlation analysis revealed significant positive correlations between the expression of LincRNA H19 and miR-675 and specific genotypes, highlighting their potential regulatory roles in tumor progression." (PMID 39267845, 2024). "Studies have shown that H19 expression levels are higher in ER-positive tumor tissues than in ER-negative ones, and that 17β-estradiol can increase H19 expression in MCF-7 cells, which are ER-positive." (PMID 38166752, 2024). "In support of this finding, increased H19 expression led to an upregulation of tumor suppressive pathways via signal decoy and ceRNA mechanisms of action, depending on its nuclear or cytoplasmic location (respectively)." (PMID 38785786, 2024). "H19 exhibits a complex array of mechanisms, demonstrating dualistic effects on tumorigenesis as it can function as both an oncogene and a tumor suppressor, contingent upon the specific context and type of cancer being investigated." (PMID 38166752, 2024). "H19 was initially thought to have a tumor-suppressive function, but recent studies have shown that it possesses both tumor-promoting and suppressive functions." (PMID 39659621, 2024). "H19 expression was inversely correlated with tumor size and vascular invasion, as well as distant metastasis (i.e., low H19 expression, increased aggressive carcinoma phenotype)." (PMID 38785786, 2024). "Based on the comprehensive collection of molecular and clinical studies discussed herein, H19 emerges as a noteworthy molecular determinant in the landscape of GC tumor initiation and progression." (PMID 38166752, 2024). "Studies have found that H19 acted as a tumor promoter gene in multiple cancer by modulating miR-148a-3p signaling pathway." (PMID 39184399, 2024). "Further in vivo assessment confirmed a role of H19 in ATC tumorigenesis, which was evaluated through a reduction in tumor volume and lung metastasis when H19 expression was reduced." (PMID 38785786, 2024). "H19 inhibited tumor metastasis in HCC by modulating the miR-200 pathway and inducing mesenchymal-to-epithelial transition (MET)." (PMID 39659621, 2024). "Experimental studies have shown that chrysin can inhibit tumor progression by regulating the H19/let-7a/COPB2, P38-MAPK/Akt and Akt/mTOR pathways and affecting mitochondrial function and ER stress." (PMID 38742934, 2024). "In lung cancer, the lncRNA H19 was known to promote tumor angiogenesis by regulating the anti-angiogenic miRNAs." (PMID 39403602, 2024). "This regulatory mechanism orchestrated by H19 contributes to the maintenance of GSCs and promotes tumor aggressiveness." (PMID 39015773, 2024). "In tumor tissues, variations in LincRNA H19 expression correlate positively with changes in miR-675 expression." (PMID 39267845, 2024). "In the realm of angiogenesis, H19 facilitates the proliferation and migration of endothelial cells, supplying the tumor with essential oxygen and nutrients." (PMID 39286016, 2024).
tumor (continued). "H19 can exert opposite effects of tumor-promoting or tumor-suppressing through different molecular mechanisms in HCC, which are related to different upstream regulatory regions and downstream pathways." (PMID 38334963, 2024). "Recent research has focused on the role of long noncoding RNAs (lncRNAs) in tumor drug resistance, especially lncRNA H19." (PMID 38794196, 2024). "H19 can regulate various biological processes through the H19/miR-675 axis by targeting oncogenic or tumor-suppressive factors, as miR-675 has numerous targets and regulates various signaling pathways." (PMID 36960964, 2023). "Fourth, tumor suppressors in the exosome constitute novel therapeutic application of exosome, including long noncoding RNA (lncRNA) H19, miR-149-5p, miR-99a-3p, and miR-423-5p." (PMID 36875488, 2023). "From the assumption above, a consequent ratio was derived from the present work of miR-let 7 to H19 demonstrating a theoretical tumor suppressor to oncogene level analysis." (PMID 36831100, 2023). "Synthetic anti-H19 constructs can be packed into small extracellular vesicles to suppress tumor growth and metastasis." (PMID 37760852, 2023). "By using Intraperitoneal DTA-H19 (BC-819), a DNA plasmid that encodes the A portion of diphtheria toxin (DTA) regulated by the promoter sequence of the H19 gene promoter, tumour size decreased by 40%." (PMID 36639695, 2023). "The earliest known tumor related lncRNAs, such as H19, were found to enhance cell proliferation, inhibit tumor cell apoptosis, and promote tumor related angiogenesis and hypoxia tolerance." (PMID 37958478, 2023). "H19 was found to be upregulated in GC tissues and cells while the downregulation of H19 suppresses the malignant phenotypes of GC cells in vitro and delays tumor growth in vivo." (PMID 37005676, 2023). "The hypoxic environment is key to the function of lncRNA RUNX1-IT1 too, which, opposite to H19, works as a tumor suppressor in hepatocellular carcinoma." (PMID 36768150, 2023). "Two imprinting control regions, one of which is ICR1 that, among other genes, harbors the IGF2 and H19 tumor suppressor genes, were also mapped." (PMID 37810933, 2023). "We discovered that H19 was highly expressed in tumor tissues and that patients with higher H19 expression have a poorer prognosis." (PMID 37821504, 2023). "Correlations between H19 and tumour dimension, invasiveness, and biochemical and hormonal parameters were evaluated." (PMID 37189829, 2023). "We discovered that lncRNA H19 overexpression augmented the tumor volume and mass, whereas Brevilin A attenuated the tumor volume and mass." (PMID 37253635, 2023). "H19 has been reported to suppress tumour growth by inhibiting the phosphorylation of 4E-binding protein 1 (4E-BP1)." (PMID 37189829, 2023). "H19 is shown to be overexpressed in GC tissues, and this overexpression relates to advanced pathological tumor stage and pathological tumor node metastasis stage; however, knockdown of H19 decreases GC cell invasion." (PMID 37005676, 2023). "Small interfering RNA-mediated knockdown of H19 in human granulosa-like tumor cell line (KGN) cells induces apoptosis and inhibits cell proliferation." (PMID 37507391, 2023). "H19 can regulate various biological processes through the H19/miR-675 axis by targeting oncogenic or tumor-suppressive factors, as miR-675 has numerous targets across multiple signaling pathways." (PMID 36960964, 2023). "For example, some preclinical studies have begun to focus on the potential of targeting certain specific lncRNAs to complete tumor therapy and related drug development, such as H19, HOTAIR, LUNAR1, etc.." (PMID 36837389, 2023). "H19 knockdown was discovered to substantially inhibit tumor growth in vivo using a nude mouse xenograft tumor model." (PMID 37821504, 2023). "Signaling pathways such as PI3K/AKT influence the tumor niche inducing different downstream events, including the expression of the H19 gene and hypoxia." (PMID 38201600, 2023).
tumor (continued). "In the xenograft model, Brevilin A repressed tumor growth, whereas lncRNA H19 fostered tumor growth." (PMID 37253635, 2023). "LncRNA H19 is considered a carcinogenic factor in GC, and its upregulation is related to tumor cell proliferation, invasion, migration, and EMT." (PMID 37691031, 2023). "For instance, the lncRNA H19 has been shown to promote tumor growth and metastasis by activating the Wnt/β-catenin signaling pathway in several types of cancer." (PMID 37232821, 2023). "Further investigations determined the role of H19 as an oncogene or, on the contrary, as a tumour suppressor." (PMID 37189829, 2023). "LncRNA H19 knockdown in TCam-2/CDDP cells can help tumor cells survive by affecting cell activity reduction, cell cycle arrest, increase apoptosis, and decrease invasion." (PMID 37781070, 2023). "This program is triggered and sustained by H19, whose high levels in hypoxic tumor regions sequester let-7, leaving the mRNA for HIF1-α and other targets, such as DICER, available for translation." (PMID 36768150, 2023). "The contribution of the different mechanisms of H19 to neoplasm origins and progression has been investigated." (PMID 37189829, 2023). "Another study showed that the expression of lncRNA H19 was frequently decreased in human primary PA and negatively related to tumor development." (PMID 37904679, 2023). "H19, the first discovered lncRNA, has key regulatory functions in tumor development and progression." (PMID 37175800, 2023). "H19: A long non-coding RNA that plays a noteworthy role in the tumor–stroma immune interplay in CRC, being modulated via extracellular vesicles/exosomes." (PMID 37760852, 2023). "The tumor was large and the tumor nodules in liver tissues were increased upon treatment with CSCs-EVs, which was negated by CSCs-EVs-sh-H19." (PMID 37005676, 2023). "TAM-derived exosomes loaded with H19 potently enhanced tumor progression, whereas H19-silenced exosomes significantly suppressed the formation of tumor mass in animal models." (PMID 37568787, 2023). "The effect of metformin on H19 lead to change in proliferation, invasion, migration, metastasis, cell cycle arrest, apoptosis, steroid receptor status, tumor size, disease-free survival, prognosis, stemness, EMT, and MET features of BC patients." (PMID 36849958, 2023). "Downregulation of the H19 expression has been shown to sensitizeleukemic cells to imatinib-induced apoptosis and inhibit tumor growth resulting from Bcr-Abltransformation." (PMID 36680478, 2023). "The expression of plasma exosome‐derived H19 was frequently downregulated in human primary PA and negatively correlated with tumor growth by restraining 4E‐BP1 phosphorylation." (PMID 37904679, 2023). "H19 can exert either a promoting role in oncogenesis or a tumor suppressor role, depending on the cell type and the established tumour microenvironment." (PMID 37143733, 2023). "An elevation was noted in the mRNA expression of H19 and CDX2 in tumor tissues of CSCs-EVs-treated mice, while CSCs-EVs-sh-H19 decreased their expression." (PMID 37005676, 2023). "Given that H19 is stable in human plasma and tissues and exhibits good repeatability, it offers great potential as a tumor marker and therapeutic target." (PMID 34644456, 2022). "An increasing number of studies are exploring the role of lncRNA during tumor development, for example, lncRNA H19 is a powerful prognostic biomarker of neuroendocrine prostate cancer that predicts the probability of tumor recurrence." (PMID 36114454, 2022). "The expression levels for MALAT1 and H19 was downregulated in tumor tissues of 62.5% and 81.25%, respectively, of OSCC patients." (PMID 35723379, 2022).
tumor (continued). "By interacting with the TCGA RNA-seq data, we found expression levels of H19 and PDXDC2P were significantly changed between tumor and adjacent normal (p-value = 9.39e−8 for H19 and p-value = 0.0083 for PDXDC2P, t-test)." (PMID 36578923, 2022). "Increasing the amount of H19 in tumor cells permits them to survive treatments, also H19 is involved in controlling BrCSCs' division by sponging microRNA let-7 which provide potential strategies for stem cell invasion and mammosphere formation." (PMID 35864503, 2022). "The function of H19 is largely dependent on the type of cancer, the stage of tumor formation, and the level of molecular signaling pathway." (PMID 36246634, 2022). "Several investigations have confirmed that H19 is a significantly expressed gene throughout embryonic development and has a role in tumor invasion and migration." (PMID 35457031, 2022). "H19 was downregulated in tumor tissues of 84.3% of OSCC patients, which is in accordance with our TCGA dataset analysis on HNSCC tumors compared to normal tissue." (PMID 35723379, 2022). "It is worth noting that H19 is highly expressed in almost all tumor tissues and plays an important role in tumor development." (PMID 34644456, 2022). "Even though the mechanism of embryo implantation in the endometrium is similar to tumor invasion, few studies on H19 in SA have been conducted." (PMID 35457031, 2022). "H19, with both oncogenic and tumor suppressor activities, acts as a double-edged sword via mechanisms such as miRNA sponging." (PMID 34489556, 2022). "H19 was upregulated in GC tissues, which induced tumor growth and metastasis through the miR−22−3p/Snail1 signaling pathway." (PMID 36405735, 2022). "A well-known long noncoding RNA, H19, has both tumor promoter and suppressive roles, those being cell type or site specific." (PMID 35723379, 2022). "In different types of cancer cells, more and more lncRNAs like lncRNA H19 (here after, referred as H19), have been verified to engage in tumor development and drug resistance of systemic therapy." (PMID 36246634, 2022). "H19 has dual roles in cancer where it can promote tumorigenesis but can also act as a tumor suppressive lncRNA through different mechanisms of action." (PMID 36033507, 2022). "The expression of NSUN2 is upregulated in HCC, which promotes tumor progression by increasing the expression level of H19 imprinted maternally expressed transcript (H19) and promoting the binding of H19 to G3BP stress granule assembly factor 1 (G3BP1)." (PMID 36120301, 2022). "By analyzing tumors of different stages, we found that the expression level of H19 increased moderately with increasing tumor stage." (PMID 36090894, 2022). "Recent evidence shows that the expression of H19 can be reactivated during regeneration and tumorigenesis in adult tissue, indicating that H19 is probably related to the development and progression of tumor." (PMID 36246634, 2022). "In the tumor tissue of patients with HBV-related HCC, H19 is significantly upregulated and is positively associated with lymph node invasion and distal metastasis, and negatively correlated with overall patient survival." (PMID 35154157, 2022). "The knockdown of H19 in T3M4 and PANC1 cells with high endogenous H19 levels suppressed cell viability, proliferation, and tumor growth." (PMID 35565245, 2022). "Upon siRNA-mediated inhibition of H19 expression, we observed reduced cell viability, migration, invasion, and tumor growth as shown here and in our previous study." (PMID 35359403, 2022). "For example, the APOBEC3G tumor promoter is preferentially induced upon induction of H19 expression by the sulforaphane bioactive agent." (PMID 35359403, 2022). "In the mouse model as well as in CRC patient samples, H19 was significantly upregulated in the tumour tissue compared to the adjacent normal colon." (PMID 36358867, 2022).